NEU1 (neuraminidase 1)
Description:
Lysosomal exo-alpha-sialidase that catalyzes the removal of sialic acid (N-acetylneuraminic acid) moieties from glycoproteins and glycolipids. To be active, it is strictly dependent on its presence in the multienzyme complex. Appears to have a preference for alpha 2-3 and alpha 2-6 sialyl linkage.
Synonyms: NANH; NEU; SIAL1
Tractability: Small molecule: a high-quality ligand is known. Antibody: its Gene Ontology location is reachable by antibodies, with high confidence; UniProt places it where antibodies can reach, with medium confidence; UniProt predicts a signal peptide or a membrane-spanning region. PROTAC: ubiquitination databases record sites on it; its protein half-life has been measured; a small molecule that binds it is known.
Target class: Enzyme; Hydrolase
Gene: Protein-coding gene on chromosome 6 (31,857,063 to 31,862,905, reverse strand). Ensembl gene ENSG00000204386.
Subcellular location: Lysosome lumen; Lysosome membrane; Cell membrane
Subcellular location (Human Protein Atlas): Vesicles; Cell Junctions
Pathways (Reactome):
Disease: Defective NEU1 causes sialidosis
Immune System: Neutrophil degranulation
Metabolism: Glycosphingolipid catabolism
Metabolism of proteins: Sialic acid metabolism
Gene Ontology:
Molecular function: exo-alpha-sialidase activity; protein binding
Biological process: oligosaccharide catabolic process; ganglioside catabolic process
Cellular component: cell junction; extracellular exosome; lysosomal membrane; lysosome; plasma membrane; cytoplasm; extracellular region; lysosomal lumen; membrane; specific granule lumen
Genetic constraint (gnomAD): Loss-of-function variants: 35 observed, 44.4 expected, observed/expected ratio (o/e) 0.79, 90% interval 0.6 to 1.04. The upper end of that interval is the gene's LOEUF score, 1.04, which puts it in group 4 of 6, group 1 being the genes least tolerant of losing a copy. Missense variants: 431 observed, 580.93 expected, observed/expected ratio (o/e) 0.74, 90% interval 0.69 to 0.8. Synonymous variants: 192 observed, 238.97 expected, observed/expected ratio (o/e) 0.8, 90% interval 0.71 to 0.91.
Gene-disease validity (ClinGen):
ClinGen rates the evidence that NEU1 causes each of these diseases.
sialidosis (autosomal recessive): Definitive.
Homologues: Orthologues: chimpanzee NEU1 (99% identical), macaque NEU1 (97% identical), pig NEU1 (86% identical), dog NEU1 (85% identical), mouse Neu1 (82% identical), rat Neu1 (82% identical), guinea pig NEU1 (81% identical), tropical clawed frog neu1 (56% identical), zebrafish neu1 (54% identical). Paralogues in human: NEU3 (25% identical), NEU4 (25% identical), NEU2 (23% identical).
Diseases named in the same sentence as NEU1 in open-access papers:
NEU1 is named in the same sentence as 166 diseases in open-access papers, as found by Europe PMC text mining. Sharing a sentence is not in itself a finding about the gene and the disease. The quoted sentences say what the papers report.
sialidosis (56 papers, 2012 to 2026). "A comprehensive understanding of the genetic variability and possible population-specific health consequences associated with sialidosis requires a thorough examination of the rates of Neu1 mutation among various ethnic groups." (PMID 40004480, 2025). "Because NEU1 is highly active toward sialylated glycoproteins, patients with sialidosis with primary NEU1 deficiency have lysosomal accumulation and massive urinary excretion of sialic acid–containing oligosaccharides." (PMID 40540388, 2025). "The relationship between mutations in the NEU1 gene and the resultant clinical features is essential for a comprehensive understanding of sialidosis." (PMID 40004480, 2025). "Sialidosis, classified into two types (type I and type II), is a rare autosomal recessive lysosomal storage disorder caused by mutations in the NEU1 gene." (PMID 40004480, 2025). "Initial discoveries in the field identified several variants in the NEU1 gene that were linked to the wide range of clinical symptoms produced by sialidosis." (PMID 40004480, 2025). "Identifying new mutations in the NEU1 gene is critical for diagnosing, treating, and investigating sialidosis." (PMID 40004480, 2025). "The molecular pathology of sialidosis is significant heterogeneity, with numerous mutations identified within the NEU1 gene." (PMID 40004480, 2025). "Lysosomal exocytosis has been implicated as the mechanism driving pathology in a mouse model of sialidosis caused by loss of lysosomal sialidase NEU1." (PMID 39641585, 2024). "Our findings indicate that rare cherry-red spots and prevalent NEU1 mutations are observed in Type I sialidosis patients in Asia." (PMID 39605025, 2024). "Sialidosis and galactosialidosis (GS) are two autosomal recessive lysosomal storage diseases (LSDs) associated with the genetic mutations of NEU1 and PPCA, respectively." (PMID 39194692, 2024). "As a result of NEU1 mutations in sialidosis, for example, the degradation of sialylated glycoproteins becomes dysregulated, accompanied by an increase in high-SA metabolites." (PMID 39194692, 2024). "In cases with a macular cherry-red spot, sialidosis should be included in the differential diagnosis, and NEU1 mutation should be screened." (PMID 39298726, 2023). "Pathogenic genetic NEU1 variants cause sialidosis (Online Mendelian Inheritance in Man [OMIM] #256550), a rare autosomal recessive disease with a prevalence of less than 1/1,000,000 live births." (PMID 37698928, 2023). "Sialidosis is an ultra-rare multisystemic lysosomal disease caused by mutations in the neuraminidase 1 (NEU1) gene." (PMID 37698928, 2023). "Together, our results demonstrated that desialylation by NEU1 plays a crucial role in processing and cellular trafficking of megalin and that NEU1 deficiency in sialidosis impairs megalin-mediated protein reabsorption." (PMID 37698928, 2023). "NEU1 variants have been divided into three categories based on biochemical properties, resulting in different subtypes of sialidosis." (PMID 35847014, 2022). "Mutations in NEU1 lead to sialidosis, a lysosomal storage disease that can either occur at an early age with marked severity (dysmorphic type) or be late-onset with mild phenotypes (cherry red spot-myoclonus syndrome or normosomatic type)." (PMID 36115840, 2022). "Sialidosis is a rare autosomal‐recessive lysosomal storage disease due to mutations in the NEU1 gene, located in 6p21.3." (PMID 35822090, 2022). "NEU1 pathogenic mutation (c.599C>T, p.Pro200Leu) has already been described in patients with sialidosis." (PMID 35822090, 2022). "Various studies report a history of recurrent infections in sialidosis patients, attributed to the impact of NEU1 deficiency on the immune system." (PMID 35847014, 2022). "LE is negatively regulated by neuraminidase 1 (NEU1), a sialidase mutated in the glycoprotein storage disease sialidosis." (PMID 36499644, 2022).
sialidosis (continued). "The most associated condition with NEU1 is sialidosis, which occurs due to mutation in the neuraminidase gene (NEU1), located on 6p21.33." (PMID 35847014, 2022). "The deficiency of NEU1 has been implicated in various pathological manifestations of sialidosis and neurodegeneration." (PMID 35847014, 2022). "In sialidosis, NEU1 deficiency and its related errors in elastin metabolism manifest typically with abnormalities that are characteristic of the early onset of sialidosis in children (such as failure to thrive, kyphosis, and facial dysmorphism)." (PMID 35847014, 2022). "The diagnosis of sialidosis is confirmed by the presence of pathogenic mutations in the NEU1 gene and reduced neuraminidase activity in cultured fibroblasts and leucocytes." (PMID 34992946, 2021). "Sialidosis, also known as mucolipidosis type 1, is a rare autosomal recessive lysosomal storage disorder caused by mutations in the neuraminidase (NEU1) gene." (PMID 34992946, 2021). "Sialidosis is caused by a genomic DNA mutation in neuraminidase 1 (NEU1) (chromosome location: 6p 21.3)." (PMID 34188220, 2021). "The clinical symptoms, severity, and penetrance of sialidosis appear to correlate with the types of NEU1 mutations, which closely reflect the overall biochemical properties of sialidase, including the levels of residual sialidase activity." (PMID 33922276, 2021). "Deficiency of NEU1 causes sialidosis with symptoms including facial dysmorphism, bone dysplasia, and neurodegeneration." (PMID 34188220, 2021). "Sialidosis, caused by a genetic deficiency of the lysosomal sialidase gene (NEU1), is a systemic disease involving various tissues and organs, including the nervous system." (PMID 33922276, 2021). "Sialidosis is a rare, autosomal recessive inherited disorder caused by α-N-acetyl neuraminidase deficiency resulting from a mutation in the neuraminidase gene (NEU1), located on 6p21.33." (PMID 35036219, 2021). "Previously, we found the novel NEU1 mutation (p.R347Q) in sialidosis patient fibroblasts showing sialidosis-associated phenotypes." (PMID 33922276, 2021). "Animal models harboring disease-causing mutations are a crucial tool for identifying and determining the common molecular mechanisms and biochemical impact of NEU1 deficiency on sialidosis-related phenotypes and pathogenesis." (PMID 33922276, 2021). "Sialidosis is an autosomal recessive lysosomal storage disorder caused by mutations in the NEU1 gene, which encodes a lysosomal neuraminidase." (PMID 32783192, 2020). "One study found that a common phenotype in sialidosis patients and Neu1-deficient mice is hepatosplenomegaly due to extramedullary hematopoiesis." (PMID 32295281, 2020). "For example, genetic deficiency of NEU1 or reduced levels of NEU1 caused by a genetic defect of Cathepsin A in humans cause sialidosis and result in galactosialidosis with lysosomal accumulations and neurodegeneration." (PMID 32752058, 2020). "Accumulation and amyloidogenic processing of an oversialylated APP in lysosomes, and extracellular release of Aβ peptides have been observed in a mouse model of sialidosis, an LSDs caused by the deficiency of the lysosomal sialidase NEU1." (PMID 32218723, 2020). "Sialidosis is caused by two enzymes: One involves acid neuraminidase (NEU1, EC 3.2.1.18), which cleaves the glycosyl bond between sialic acid and oligosaccharides." (PMID 32295281, 2020). "Sialidosis is caused by the deficiency of alpha-N-acetyl neuraminidase due to mutations in the neuraminidase 1 gene (NEU1) resulting in the accumulation of sialylated glycoconjugates." (PMID 32957425, 2020). "Sialidosis is caused by progressive accumulation of sialylated glycopeptides andoligosaccharides due to neuraminidase 1 (NEU1) deficiency, also known assialidase." (PMID 31132295, 2019).
sialidosis (continued). "Age of onset and severity of the clinical manifestations are paralleled with NEU1 mutations and the level of residual neuraminidase activity, demonstrating the existence of significant genotype-phenotype correlation in sialidosis." (PMID 29693572, 2018). "NEU1 deficiency causes severe systemic disorders, sialidosis and GS associated with pathological changes in the CNS." (PMID 30088207, 2018). "Genetic deficiency of NEU1 in humans results in a severe metabolic disease, sialidosis (OMIM #256550), caused by the lysosomal storage of sialylated glycoproteins and oligosaccharides." (PMID 30088207, 2018). "To date, NEU1 has been the most studied sialidase, notably because NEU1 deficiency is linked to genetic diseases, sialidosis and galactosialidosis." (PMID 27917893, 2016). "Among them, NEU1 initiates the catabolism of sialo-glycoconjugates by removing their terminal sialic acid residues, and mutations in Neu1 gene cause sialidosis in humans." (PMID 26731280, 2016). "Two neurodegenerative lysosomal storage disorders, sialidosis and galactosialidosis are attributed to deficiency of NEU1." (PMID 26569607, 2015). "Mutations in NEU1 gene have been identified in patients affected by neuraminidase deficiency or sialidosis (MIM 256550), a severe lysosomal storage disorder showing autosomal recessive heritability." (PMID 25153125, 2014). "Since we are mainly interested in variants affecting the function of the NEU1 enzyme, as possible pathological alleles in sialidosis, we focused our further analysis only on SNVs occurring in the CDS of this gene." (PMID 25153125, 2014). "Mutations in NEU1 gene are causative of sialidosis (MIM 256550), a severe lysosomal storage disorder showing autosomal recessive mode of inheritance." (PMID 25153125, 2014). "In vitro functional studies on variants occurring in NEU1 gene also led to the identification of two new putative disease-causing mutations responsible for sialidosis." (PMID 25153125, 2014). "Comprehensive investigations that integrate genetic analysis with functional and structural evaluations are crucial for comprehending the influence of new mutations on the function of the NEU1 gene and the correlation between genotype and phenotype in sialidosis." (PMID 40004480, 2025). "Sialidosis is an autosomal recessive disorder caused by pathogenic mutations in the NEU1 gene, which is localized on chromosome 6p21.3 and encodes neuraminidase 1 (NEU1)." (PMID 39350194, 2024). "Mutation in neuraminidase 1, NEU1 (sialidase 1), a lysosomal enzyme that plays a crucial role in the catabolism of sialo-glycoconjugates, leads to lysosomal storage disorder sialidosis, while abnormal NEU1 activity has been implicated in cancer progression, inflammation, and immune response." (PMID 39628991, 2024). "Sialidosis is a hereditary metabolic disorder caused by mutations in the NEU1 gene." (PMID 39605025, 2024). "Therefore, AAV-mediated gene therapy appears a suitable treatment for sialidosis and other diseases associated with low NEU1 expression." (PMID 39194692, 2024). "Thus, the treatment of NEU1 mRNA expression with HDACi caused an upregulation of the levels of mutant NEU1 mRNA as well as an increase in the residual activity in fibroblasts extracted from patients with Sialidosis." (PMID 35847014, 2022). "The various NEU1 mutations and the related residual neuraminidase activity are somewhat correlated with both the severity of the clinical manifestations and the onset age, demonstrating the existence of significant genotype–phenotype correlation in sialidosis." (PMID 35822090, 2022). "Furthermore, studies of sialidosis patients have shown that the genetic deficiency of NEU1 results in impaired insulin-induced phosphorylation of downstream protein kinase AKT." (PMID 35847014, 2022). "NEU1 deficiency is most commonly associated with sialidosis." (PMID 35847014, 2022).
sialidosis (continued). "In a mouse model of sialidosis, the deficiency of the lysosomal sialidase NEU1 (neuraminidase 1) leads to the accumulation of an oversialylated amyloid precursor protein in the lysosomes and extracellular release of amyloid β (αβ) peptides by excessive lysosomal exocytosis." (PMID 36285443, 2022). "Also, experimental studies on cultured dermal fibroblasts from patients with lysosomal β-galactosidase, PPCA, and Neu-1 deficiencies (such as congenital sialidosis and galactosialidosis." (PMID 35847014, 2022). "Sialidosis is a rare autosomal‐recessive lysosomal storage disease due to mutations in the NEU1 gene leading to a deficit of alpha‐n‐acetyl neuraminidase and causing aberrant accumulation of sialylated glycoproteins/peptides and oligosaccharides in the lysosomes of various organs and tissues." (PMID 35822090, 2022). "Large numbers of neurological cell models, covering various types of heterogeneous pathological mutations in NEU1 gene, are highly desirable to clearly define the neuropathological defects of sialidosis caused by NEU1 mutation and to develop novel therapeutic strategies." (PMID 33922276, 2021). "In pursuit of more accurate and reproducible modeling of sialidosis, multiple iPSC models, covering various types of heterogeneous pathological mutations in NEU1 gene, a variety of donors, and differentiation variation, are highly desirable for comparative studies, but still are not available." (PMID 33922276, 2021). "Characterization of NEU1G227R- and NEU1V275A/R347Q- mutated iNPCs derived from sialidosis-iPSCs (sialidosis-iNPCs) validated that sialidosis-iNPCs faithfully recapitulate key disease-specific phenotypes, including reduced NEU1 activity and impaired lysosomal and autophagic function." (PMID 33922276, 2021). "Genetic testing of sialidosis patients has revealed various pathological variants of the NEU1 gene that are related to a broad range of neurophysiological abnormalities, including visual defects, myoclonus syndrome, cherry-red macular spots, ataxia, hyperreflexia, and/or seizures." (PMID 33922276, 2021). "Notably, rapamycin was less effective in inducing autophagy in the sialidosis-iNPCs than in the normal-iNPCs, which confirmed the Neu1 deficiency-associated inhibition of the autophagic flux in sialidosis-iNPCs." (PMID 33922276, 2021). "As a tissue-specific disease model, retinal pigment epithelial cells (RPEs) were produced from a salidosis-iPSC model with NEU1 mutations c.239C > T and c.403G > A and thereby revealed the NEU1 deficiency-associated impaired autophagy in sialidosis-specific RPEs." (PMID 33922276, 2021). "Human Tay-Sachs patients have mutations in the HexA gene encoding for lysosomal β-hexosaminidase A resulting in accumulation of GM2 ganglioside, while sialidosis patients have mutations in the neuraminidase 1 (NEU1) gene, leading to lysosomal storage of sialylated glycoproteins." (PMID 34156977, 2021). "All NEU1G227R- or NEU1V275A/R347Q-mutated iNPC models showed NEU1 deficiency-mediated autophagy and lysosomal dysfunction and loss of differentiation capacity, which were closely related to neurological dysfunction that occurred because of sialidosis." (PMID 33922276, 2021). "However, only four reports have been published on sialidosis-iPSC models from patients with different NEU1 mutations." (PMID 33922276, 2021). "Sialidosis is characterized by accumulation of sialic acid-containing compounds (mainly sialyloligosaccharides and sialoglycoproteins) in cells caused by a functional loss of lysosomal NEU1 (sialidase, acid neuraminidase, EC 3.2.1.18)." (PMID 32272755, 2020). "Congenital deficiency of the lysosomal sialidase neuraminidase 1 (NEU1) causes the lysosomal storage disease, sialidosis, characterized by impaired processing/degradation of sialo-glycoproteins and sialo-oligosaccharides, and accumulation of sialylated metabolites in tissues and body fluids." (PMID 32143456, 2020).